PYCR1 (pyrroline-5-carboxylate reductase 1)
Diseases named in the same sentence as PYCR1 in open-access papers (continued):
Sharing a sentence is not in itself a finding about the gene and the disease.
cancer (continued). "Additionally, cancer metabolism-related genes, including PFKM, IDH3G, PYCR1, and BCAT1, were strongly elevated in expression in response to increased LINC00473 levels." (PMID 38512964, 2024). "Similarly, the significantly downregulated genes included CHAC1, SLC7A11, PYCR1, PSPH, and DDIT4, among others, with these genes being involved in iron death, cancer cell expansion, and apoptosis (15, –, 19)." (PMID 38299864, 2024). "Additionally, the discovery of the molecular link between PYCR1 and IRS1 provides a valuable framework for understanding metabolic and epigenetic alterations in cancer cells." (PMID 39422696, 2024). "Altogether, our study reveals that PYCR1-synthesized proline activates the cGMP-PKG signaling pathway to enhance TNBC stem-like properties and that cGMP-PKG signaling mediates psychological stress-induced cancer stemness and progression." (PMID 37845207, 2023). "Similarly to inhibiting PYCR1, BMS303141 opposed cancer cell proliferation, which was restored by acetate, while having no significant impact on CAF growth." (PMID 35760868, 2022). "Accumulation of the PYCR1 protein was also confirmed by western blot analysis performed on primary cells isolated from surgically resected colon neoplasia and adjacent normal tissue, as well as by assessment of a panel of CRC cancer cell lines." (PMID 35130302, 2022). "PYCR1 inhibition in CAFs in the coculture significantly reduced the proliferation of cancer cells but not CAFs." (PMID 35760868, 2022). "Inhibitors of cancer targets are useful as chemical probes for studying cancer mechanisms and starting compounds for drug discovery; however, there is a notable lack of validated inhibitors for PYCR1." (PMID 33109600, 2020). "The clinical proteomic results identified PYCR1 as a candidate cancer regulator irrespective of cancer subtype, while having stronger association with hormone‐positive tumors." (PMID 32960509, 2020). "However, the role of PYCR1 in PRCC is still unclear, although targeted drug treatment is regarded as an effective method for delaying cancer metastasis." (PMID 31428683, 2019). "The role of PYCR1 in cancer is not entirely clear, but it probably relates to the biosynthesis of proline and potentially production of collagen for the extracellular matrix." (PMID 23024808, 2012). "However, the specific mechanism responsible for the role of PYCR1 in cancer development and progression has not been adequately elucidated." (PMID 34239351, 2021). "It is known that the roles of ACADSB, ACADM, HADH, PYCR1 and ITPKA have been explored in cancers, whereas PAFAH2 not12–16." (PMID 37460577, 2023).
infection (7 papers, 2015 to 2024). The state of being infected such as from the introduction of a foreign agent such as serum, vaccine, antigenic substance or organism. "In the present study, four host genes (Gm15587, Nos2, Pycr1, Arg2) were enriched in this metabolic pathway, two of which (Nos2, Pycr1) were downregulated in the infection group." (PMID 32509459, 2020). "After infection, the expression of PYCR1 protein was detected by Western blot." (PMID 35371311, 2022).
kidney disease (1 paper, 2019). "Physiological relevance with regard to kidney disease as indicated by literature research was found for two proteins (PYCR1, FXYD2)." (PMID 31083566, 2019).
PYCR1 also shares sentences with these, for which no sentence is quoted: gastric cancer (8 papers); lymphoma (4); pancreatic ductal adenocarcinoma (4); Anxiety (2); cardiovascular disease (2); Clear Cell Renal Cell Carcinoma (2); esophageal squamous cell carcinoma (2); genetic disorder (2); hyperprolinemia (2); invasive breast carcinoma (2); triple-negative breast carcinoma (2); aging (1); aortic root dilatation (1); autism (1); cardiac diseases (1); cataract (1); colorectal tumor (1); corneal clouding (1); coronary heart disease (1); De Barsy syndrome A (1); De Barsy syndrome B (1); dementia (1); Escobar syndrome (1); glioblastoma (1); hematological cancers (1); hepatoblastoma (1); hyperprolinemia type 2 (1); Infertility (1); Intellectual disability (1); invasive ductal carcinoma (1).
A further 14 diseases each share a sentence with PYCR1 in 1 paper.